TNF (tumor necrosis factor)
Diseases named in the same sentence as TNF in open-access papers (continued):
Sharing a sentence is not in itself a finding about the gene and the disease.
uveitis (continued). "HLA-B27 positivity is associated with higher TNFα levels in active uveitis." (PMID 24991219, 2014). "We showed that IFN-γ, IL-17A, TNF-α, and hsCRP are increased in active uveitis associated with BD." (PMID 24994946, 2014). "During the last few years, tumor necrosis factor-alpha (TNF-α) blocking agents (infliximab, etanercept, and adalimumab) have been used to treat chronic refractory uveitis in childhood and, particularly, uveitis associated with JIA in children who have failed topical and second-line DMARD therapy." (PMID 24489444, 2013). "The reason for the difference between the various TNF inhibitors and risk of developing uveitis is unknown, but it may reflect a differential alteration of the cytokine milieu and/or differential effectiveness in treating intraocular inflammation." (PMID 23522744, 2013). "Furthermore, the uveitis seen in leptospirosis is associated with a rise in IL-6, IL-8, TNF-α, and IL-10 production." (PMID 23132959, 2012). "Rituximab may represent rescue therapy for severe JIA-associated uveitis refractory to traditional immunosuppressives and TNF-α inhibitors." (PMID 22454752, 2011). "Anti-TNF-α agents (e.g., infliximab) achieve corticosteroid sparing control in refractory uveitis (adult and pediatric cohorts), while anti-IL-6R (tocilizumab) is effective for uveitic cystoid macular edema and in juvenile idiopathic arthritis associated uveitis refractory to anti-TNF therapy." (PMID 41169366, 2025). "Previous studies have reported that the majority of infiltrated cells within the retina after uveitis inflammation were F4/80+ macrophages, which could produce proinflammatory cytokines, such as IL-1β and TNF-α, and contribute to uveitis-associated inflammation." (PMID 37878302, 2023). "Therefore, an anti-TNF should be preferred if IBD or recurrent uveitis is associated." (PMID 37654637, 2023). "Furthermore, anti-TNF-α antibody therapy is linked to side effects such as sarcoidosis, uveitis, and nervous system disorders; and immunosuppression associated with TNF-α blockade is a significant risk factor for exacerbation of disease pathology in SARS-CoV-2 infected individuals." (PMID 37854602, 2023). "Many studies have observed a constant increase in TNF-α expression in inflammatory cell infiltrates, not only in various models of experimental uveitis, but also in RPE and Müller cells, which causes these cells to possess uveitogenic properties and might decisively influence the course of EAU." (PMID 34795583, 2021). "This trial is a novel adaptive design study of subcutaneous IL-6 inhibition in anti-TNF refractory JIA associated uveitis which will be able to determine if further research into the use of this intervention for the treatment of anti-TNF refractory JIA-associated uveitis should be conducted." (PMID 30886955, 2018). "Additionally, a recent study showed that systemically injected etanercept effectively prevented retinal ganglion cell loss in a rat model of glaucoma in which TNF-α and its receptor were detected at high levels, as well as in rats with endotoxin-induced uveitis." (PMID 27259948, 2016). "In fact, we did not observe differences in the cytokine profile between Caucasian and African patients (data not shown), which allows us to speculate that the observed increased levels of IFN-γ, TNF-α, and IL-17A may apply to uveitis associated with BD from any origin." (PMID 24994946, 2014). "Uveitis has been described as a rare adverse event of anti-TNF-α therapy, and in a retrospective study four patients were described with a co-occurrence of HS and uveitis, two with anterior uveitis, one with iridocyclitis and one with panuveitis." (PMID 41142785, 2025). "Biologic agents, particularly tumor necrosis factor-α (TNF-α) inhibitors, have revolutionized uveitis management by targeting specific inflammatory pathways." (PMID 41303213, 2025).
uveitis (continued). "All TNF-α inhibitors demonstrated strong signals for uveitis (ROR = 23.89, 95% CI [20.16–28.22], n = 308), particularly adalimumab (ROR = 20.96, 95% CI [17.82–24.65], n = 145) and golimumab (ROR = 52.08, 95% CI [31.07–87.33], n = 15)." (PMID 41329755, 2025). "Although switching from adalimumab to the IL-17 inhibitor ixekizumab was initially considered, a within-class switch to another TNF inhibitor, certolizumab pegol, was ultimately chosen because of the strong evidence of TNF inhibitor effectiveness for uveitis." (PMID 40709135, 2025). "Monoclonal tumor necrosis factor (TNF) inhibitors, commonly used in managing AS, have demonstrated significant efficacy in controlling uveitis." (PMID 41007651, 2025). "Drugs targeting tumor necrosis factor-α(TNF-α) are considered first-line immunomodulatory therapy for uveitis, with antimetabolites more commonly used as adjuvant or second-line therapy." (PMID 40072972, 2025). "Targeting IL-1 and TNF-α with biologic therapies has shown efficacy in the treatment of uveitis, particularly in cases that are refractory to conventional immunosuppressive agents." (PMID 40433375, 2025). "Adalimumab, an FDA-approved anti-TNF agent for uveitis, is a fully humanized IgG1 monoclonal antibody that neutralizes tumor necrosis factor (TNF)-alpha activity and induces apoptosis of TNF-expressing cells." (PMID 40087200, 2025). "Patients with uveitis who were treated with anti-TNF-α antibodies presented significantly fewer side effects than those who were using corticosteroids." (PMID 40943417, 2025). "The activation of glucocorticoid receptor isoform alpha (GRα) by CS results in anti-inflammatory effects in uveitis, suppressing the production of pro-inflammatory cytokines, such as IL-1, IL-6, and TNF-α, by blocking their transcription." (PMID 40433375, 2025). "The pathophysiology of uveitis, one of the most common extra-musculoskeletal manifestations of axSpA, is complex and multiple potential therapeutic targets including IL-17 and TNF-alpha have been identified." (PMID 39798135, 2025). "Studies investigating the recurrence rate of uveitis in patients with AS undergoing TNF inhibitor spacing are scarce." (PMID 41007651, 2025). "Recent studies have shown that anti-TNF-α agents can be effective in treating inflammatory diseases related to HTLV-1 (such as arthropathy, uveitis, and other rheumatic conditions associated with the given viral infection)." (PMID 41020241, 2025). "The network showed that LXD exerted therapeutic effects upon valuable targets participated in the genesis and development of uveitis, including Notch1, IL-6, IL-2, TNF, and IL-10." (PMID 40918405, 2025). "The distinct presence of pro-inflammatory cytokines like IFN-γ and TNF-α in BU, compared to other forms of uveitis, suggests the potential for novel therapeutic strategies." (PMID 38778397, 2024). "Research has demonstrated that TNF-α levels are elevated in the aqueous humor and vitreous fluid of patients with uveitis, correlating with the severity of the disease." (PMID 39449328, 2024). "The involvement of TNF-α has been observed in various autoimmune diseases, such as uveitis, rheumatoid arthritis, MS, and inflammatory bowel disease." (PMID 38891990, 2024). "While TNFα is readily detected in the ocular tissues and aqueous humor of uveitis-affected eyes, the concentration is much lower in healthy equine eyes." (PMID 39867889, 2024). "In the context of recurrent uveitis, TNFα is thought to disrupt the blood–retina barrier, promote proinflammatory immune cell influx into the eye, and play a critical role in disease progression." (PMID 39867889, 2024). "In the context of uveitis, TNF-α contributes to disruption of the blood–ocular barrier, recruitment of inflammatory cells, and exacerbation of intraocular tissue damage." (PMID 39449328, 2024).
uveitis (continued). "Consensus-based recommendations advise in class switching if uveitis is refractory to a first anti-TNFα although evidence to support this approach is limited." (PMID 37848676, 2024). "In recent decades, the development of drugs targeting TNF-alpha has been one of the main keys in the treatment of multiple inflammatory processes, including uveitis." (PMID 39685848, 2024). "TNF inhibitors are increasingly used in patients with BD since the approval of adalimumab in 2016 for the treatment of uveitis." (PMID 38180499, 2024). "Currently, TNFα blockers are used in several diseases, including human recurrent uveitis, as a therapeutic strategy to limit excessive TNFα signaling." (PMID 39867889, 2024). "A total of seven other detailed cases were identified reporting induced demyelination related to the use of anti-TNF medications specifically for uveitis." (PMID 39078559, 2024). "The pro-inflammatory cytokine TNF-α is believed to be a pivotal factor in uveitis inflammation, with upregulated levels in both aqueous humor and serum among uveitis patients." (PMID 39157460, 2024). "Currently, there is very limited literature describing successful alternative long-term management specific to uveitis patients presenting with neurological symptoms while being on an anti-TNF agent." (PMID 39078559, 2024). "Clinical trials have shown ADA to have a better safety and efficacy profile than other anti-TNF inhibitors (i.e., infliximab and etanercept) for managing pediatric uveitis." (PMID 39254907, 2024). "The proinflammatory cytokine tumor necrosis factor α (TNF-α) is considered a major factor in ocular/uveitis inflammation." (PMID 38800327, 2024). "ADA is a humanized monoclonal antibody that inhibits tumor necrosis factor (TNF)-alpha, an inflammatory cytokine involved in the pathogenesis of uveitis." (PMID 39254907, 2024). "Both analyses resulted in consistent findings with previous research highlighting the efficacy of anti-TNFα monoclonal antibodies for the treatment or prevention of uveitis." (PMID 38337605, 2024). "Based on this fact, inhibiting TNF-α seems to be a potentially effective therapeutic strategy for uveitis." (PMID 39407875, 2024). "There is growing interest in the localized management of uveitis through intravitreal injections of anti-TNF agents." (PMID 38778397, 2024). "In severe cases of uveitis, biologic medications are employed, encompassing TNF-α inhibitors and antibodies targeting interleukins as well as B and T lymphocytes." (PMID 39062219, 2024). "In summary, in BD uveitis pro-inflammatory cytokines such as Il-6, TNFα, ΙFNγ, and IL-1ra are increased in AH." (PMID 37297843, 2023). "Interleukin 6 (IL-6) plays a central role in the pathogenesis of autoimmune diseases, and its inhibition has been recently shown to be effective in treating the most severe cases of uveitis that are unresponsive even to anti-TNF agents." (PMID 37700264, 2023). "Adalimumab, one of anti-tumor necrosis factor (anti-TNF) drugs, is an approved biologic therapy for uveitis, of which the efficacy and safety were shown in phase 3 randomized-controlled trials involving patients with VKH disease." (PMID 37355662, 2023). "In 4 of them, uveitis occurred despite they were already on treatment with bDMARDs (2 with monoclonal antibodies against TNF, 1 with etanercept and one with secukinumab)." (PMID 37610650, 2023). "TNFα inhibitors are excellent options since studies have demonstrated that TNFα inhibitor antibodies significantly reduce uveitis flares (RR 7.4)." (PMID 37646883, 2023). "In fact, patients with uveitis experience an increase in vascular permeability due to the release of inflammatory mediators, such as TNFα, IL-6, IL-8, IL-17, or IL-23." (PMID 36986627, 2023). "The same authors reported in 2015 a similar case of leishmaniasis recurrence with mucosal localization after VL caused by L. infantum in a 4-year-old girl affected by juvenile idiopathic arthritis and bilateral uveitis treated with anti-TNFα." (PMID 37764934, 2023).
uveitis (continued). "According to the European League Against Rheumatism (EULAR) guidelines, TNF-α inhibitors are recommended for BD patients with uveitis resistant to colchicine, corticosteroids, and various immunomodulators." (PMID 36744150, 2023). "Several signaling pathways were closely associated with uveitis, including Toll-like receptor, Il-17, MAPK, TNF, and NOD-like receptor signaling pathways, suggesting that SNS can act on uveitis through multiple channels." (PMID 37653797, 2023). "We aimed to determine medium and long-term effects of TNF-α inhibitors in patients with pediatric uveitis." (PMID 36831165, 2023). "While TNFα is generally thought to participate in the pathogenesis of uveitis, and anti-TNF drugs are effective for panuveitis and posterior uveitis treatment, IL-17A and IL-17F are also reported to be involved in anterior uveitis progression." (PMID 37238999, 2023). "Due to the decreased availability of intravenous tocilizumab during the COVID-19 pandemic, we started using the subcutaneous formulation of the drug in children with anti-TNF refractory uveitis." (PMID 37700264, 2023). "Consistent with previous studies, we found that AGO and RAME reduced TNF-α levels induced by uveitis." (PMID 37051104, 2023). "The study analyzes the serum concentration of tocilizumab and its clinical response in patients with anti-TNF refractory uveitis who started or switched to subcutaneous administration from intravenous use." (PMID 37700264, 2023). "Another study showed that TNF receptor (TNF-R) and TNFα levels were elevated in ocular fluids from patients with active uveitis, and blocking the TNF-R resulted in an increase in TNFα production by T cell populations." (PMID 36652160, 2023). "Numerous studies have confirmed the favourable results both in efficacy and safety of biological drugs, mainly molecules against tumour necrosis factor α (TNFα), in patients with uveitis refractory to conventional treatments." (PMID 36986627, 2023). "For instance, studies using a uveitis rat model reported a significant upregulation of IL‐1β and TNF‐α gene expression in the stage of active intraocular inflammation." (PMID 36988248, 2023). "In earlier reports on visual outcome prior to the use of TNF-α inhibitors for the treatment of refractory BD uveitis, 20–74% of patients became legally blind with visual acuity of 20/200 or less within 10 years after the onset of uveitis." (PMID 36744150, 2023). "For example, TNF-α plays an important role in the pathogenesis of intestinal lesions and uveitis, whereas IL-23/IL-17 pathway plays a major role in skin lesions." (PMID 37485474, 2023). "In conclusion, we reported on cases of effective use of subcutaneous tocilizumab to treat pediatric patients with TNF-refractory uveitis." (PMID 37700264, 2023). "The results of the present study demonstrated that TNF-α inhibitors achieved rapid control of pediatric uveitis while enabling a remarkable systemic and topical corticosteroid-sparing effect." (PMID 36831165, 2023). "It has been shown that ANXA1 (Ac2-26) reduces the production of proinflammatory cytokines, such as TNF-α, IL-1β and IL-6, in LPS-induced uveitis." (PMID 36544058, 2023). "Anti–TNF-α agents for uveitis, such as infliximab and adalimumab, are increasingly analyzed in clinical studies." (PMID 37878302, 2023). "Calvo-Rio et al15 conducted an open-label, interventional case-series to assess the clinical response of refractory uveitis in patients with BD to anti-TNF therapy." (PMID 37493653, 2023). "The treatment approaches of 377 patients who received first-choice anti-TNF agent treatment for JIA and JIA-associated uveitis in Umraniye Training and Research Hospital between 2016-2023 were evaluated retrospectively." (PMID 37848930, 2023). "Herpes and toxoplasmosis are the leading causes of uveitis, and both Th1 and Th17 T cells and cytokines such as IL-6 and TNF-α are involved in the pathogenesis of uveitis." (PMID 36424630, 2022).
uveitis (continued). "Methotrexate and more recently anti-tumor necrosis factor alpha (TNFα) have allowed a marked improvement in the functional prognosis of severe inflammatory pediatric uveitis, as demonstrated in the ADJUVITE and SYCAMORE trials." (PMID 35311049, 2022). "Bringing out decision factors for initiating anti-TNFα therapy should help to establish guidelines in pediatric uveitis management." (PMID 35311049, 2022). "Previous investigations have showed the increased expression of circulating CRP, IL-6 and TNF-α in the uveitis." (PMID 36275682, 2022). "–31 In LPS-induced uveitis in the rabbit, treatment with anti-TNF-α effectively lowered the disease score, further highlighting the mechanistic role of TNF-α in uveitis." (PMID 35579886, 2022). "Case reports and retrospective case series in children all reported favourable outcomes in BD uveitis with anti-TNF use, especially with adalimumab." (PMID 35268369, 2022). "It is most important to keep in mind that uveitis patients with LTBI must have INH prophylaxis with 300 mg/d for at least 9 months in case of initiating TNF-alpha-inhibiting treatment." (PMID 35566544, 2022). "Blocking TNF thus appears to be a viable strategy to treat not only uveitis, but possibly also DR and AMD." (PMID 35251042, 2022). "Prescribing habits in JIA uveitis are quite easily oriented toward anti-TNFα studies having shown an important efficacy of this treatment." (PMID 35311049, 2022). "Anti‐TNF is usually used in refractory Behcets disease manifestations, mainly sight‐threatening disease with frequent relapse of uveitis in addition to other refractory manifestations, but its use in sensorineural hearing loss is less well established." (PMID 36254147, 2022). "Eleven patients with active TIN were escalated to MMF, while those who remained active for uveitis had their treatment escalated to either Methotrexate (2 patients) or anti-TNF treatment (1 patient) having good response to the treatment." (PMID 36096831, 2022). "Previous studies have found that TNF-α played an important role in the occurrence and development of uveitis by affecting the transcription regulation and protein expression levels of TNF-α." (PMID 36530572, 2022). "Subcutaneous humanized mAb adalimumab is now the anti-TNF-alpha biologic most commonly used for uveitis in clinical practice." (PMID 35566597, 2022). "Elevated TNF-α levels have also been demonstrated to play a mechanistic role in uveitis, a vision-threatening disease characterized by severe intraocular inflammatory processes." (PMID 35579886, 2022). "Of note, most of these investigations have compared active with inactive uveitis or a healthy control group showing increased serum levels of different cytokines in the active group, such as the IL-8, IL-6, TNF-α, IL-17, IL-21, IL-23." (PMID 36498608, 2022). "Although uveitis represents a phenotypically heterogeneous group of intraocular inflammatory conditions, they have in common raised levels of TNF-α in both serum and aqueous humor." (PMID 36530572, 2022). "In accordance with these findings, TNFα plays a major role in human uveitis and has been detected in human patients following phacoemulsification surgery." (PMID 35998207, 2022). "Again, anti-TNF-α or anti-IL-6 treatment improves the induced pathologies in diverse uveitis models." (PMID 36371417, 2022). "HUMIRATM, a human monoclonal antibody ‘adalimumab’ is a TNFα inhibitor, which has shown positive results in the treatment of uveitis in humans." (PMID 35998207, 2022). "d-MAPPSTM contains soluble receptors of tumor necrosis factor alpha (sTNFRI, sTNFRII) and growth-related oncogene gamma (GRO-γ), which are able to prevent IL-1β-, TNF-α-, and IL-12-driven uveitis." (PMID 36362313, 2022). "Currently, TNF-α blocking agents are the main biologics used as treatment of chronic childhood uveitis although in unresponsive JIA uveitis cases other biological drugs options are available." (PMID 34669094, 2022).